MMP2 (matrix metallopeptidase 2)
Diseases named in the same sentence as MMP2 in open-access papers (continued):
Sharing a sentence is not in itself a finding about the gene and the disease.
tumor (continued). "It selectively binds to tumor cells through interactions with Annexin A2 and matrix metalloproteinase-2 (MMP-2)." (PMID 40867331, 2025). "It reduces the expression of chemokines MCP-1 and RANTES, which are essential for TAM recruitment, and further suppresses TAM activation by decreasing M2 macrophage markers and tumor-promoting factors like MMP-2, MMP-9, and VEGF." (PMID 40330466, 2025). "When isorhamnetin interacts with the cancer cell, it downregulates key molecular markers playing a key role in tumor progression, including MMP-2 and MMP-9 (matrix metalloproteinases accountable for degrading the basement membrane)." (PMID 40806510, 2025). "Together, these results confirm that the oncogenic PLEKHA1-TACC2 fusion protein activates the EphA2/AKT/MMP2 signaling pathway through stabilizing EphA2 expression and plays a vital role in tumor VM formation." (PMID 40615663, 2025). "Traditionally, MMP-2 is known for its role in promoting tumor invasion, metastasis, and angiogenesis by degrading the extracellular matrix and basement membrane." (PMID 40611940, 2025). "In experimental studies, laboratory animals in which MMP-2 expression is inhibited show reductions in angiogenesis, tumour growth and metastatic capacity." (PMID 40724562, 2025). "A tumor-penetrating nanovesicle sensitive to matrix metalloproteinase-2 (MMP-2) was designed to target cholesterol metabolism and enhance photodynamic cancer immunotherapy." (PMID 40270603, 2025). "Reducing the expression of MMP‐2 proteins is related to the inhibition of proliferation, clonal growth, and metastasis, promoting the apoptosis of tumor cells." (PMID 40400263, 2025). "MMP-16 (MT3-MMP) is located on chromosome 8 and is a membrane-bound protease that modulates MMP-2 and -9 activation, influencing tumor invasion and cell migration." (PMID 41281748, 2025). "The cell-type-specific (defined based on marker gene expression profiles and clustering analysis) expression of CD44, FGF2, FGF10, KDM6A, FN1, and MMP2 in the tumor microenvironment of UCEC was analyzed using the TISCH2 database." (PMID 39833941, 2025). "Leveraging its extended blood circulation and precise tumor targeting via PEGylated shell and GE11-modified HA backbone, nanoCRISPR activates its self-cascade mechanism upon encountering the MMP2 enzyme-rich tumor microenvironment." (PMID 41311390, 2025). "The secretion of COL17A1 and MMP2 by these cells enhances their migratory capabilities and contributes to the formation of a fibrotic stroma that facilitates tumor progression." (PMID 40770187, 2025). "Within the TME, MMP-2 enzymatically cleaves the peptide linker, releasing iRGD, which promotes tumor infiltration, while simultaneously triggering the co-release of AVA and PPa." (PMID 41345744, 2025). "As a zinc-dependent endopeptidase, MMP-2 degrades the extracellular matrix, facilitating tumor cell migration and invasion." (PMID 40732329, 2025). "MMP-2 is secreted by stromal cells, which explains its stimulatory role on invasiveness through tumour cell interactions with stromal cells." (PMID 40724562, 2025). "The MMP-3 was found to be more expressed in healthy stroma compared to tumor stroma, and MMP-2 was more expressed in T cell tumors compared to B cell tumors, a similar result to BDNF." (PMID 40427122, 2025). "After the SH intervention, the levels of the tumor angiogenesis-related genes MMP-2, VEGFA, VEGFC, VAV2, and LARP1 were significantly downregulated when compared with the Model group, whereas the GADD45A level was markedly upregulated." (PMID 41444284, 2025). "Downregulating MMP-2 expression can suppress tumor cell proliferation, growth, and metastasis, while enhancing tumor cell death." (PMID 40894070, 2025). "The histone deacetylase inhibitor (HDAC) valproic acid downregulates MMP-2 and MMP-9 expression, reduces stem-cell-associated properties and tumor metastatic potential, and promotes the anaplastic redifferentiation of tumor cells." (PMID 40565017, 2025).
tumor (continued). "These nanoparticles remain stable in circulation but release their anti-PD-L1 payloads specifically in tumor regions with high MMP-2 expression." (PMID 40909221, 2025). "MMP-2 and MMP-9 are enzymes that play a crucial role in extracellular matrix regulation and have been implicated in the process of tumor migration and invasion." (PMID 40940722, 2025). "Fibroblasts can also regulate the expression of matrix metalloproteinases such as MMP2, affecting tumour cells’ growth and metastasis." (PMID 39950116, 2025). "The nanostructure swelled when it encountered the weakly acidic tumor niche where DEAP molecules were protonated and further collapsed due to the cleavage of the peptide substrate by MMP-2 that is highly expressed in tumor stroma." (PMID 40343307, 2025). "The thioredoxin (Trx) tag enhances the solubility and stability of the fusion protein, while the MMP-2/9-cleavable peptide (PVGLIG) ensures responsiveness to the tumor microenvironment by being cleaved in the presence of overexpressed MMP-2/9 enzymes." (PMID 40444089, 2025). "The specific role of integrin αvβ3 in tumor infiltration and metastasis is attributed to its ability to recruit and activate MMP-2 and fibrinolytic enzymes, thereby degrading stromal membranes and mesenchymal matrix components." (PMID 41160271, 2025). "VE-cadherin is essential for VM channel stability, LAMC2 mediates extracellular matrix (ECM)–tumor interactions, and MMP-2 facilitates ECM degradation to enable invasion and channel formation." (PMID 41463012, 2025). "MMP-14 or MT1-MMP is also a promising target due to its role in local ECM degradation and in activating other MMPs, including MMP-2, on the tumor cell surface." (PMID 40265458, 2025). "THC and CBD upregulate TIMP-1, which inhibits matrix metalloproteinase 2 (MMP2) and blocks tumour angiogenesis and invasion." (PMID 41102423, 2025). "The GPLGVRG peptide was designed to enhance PTX liposome accumulation in tumor microenvironments by leveraging MMP-2-mediated peptide degradation, which triggered the detachment of long-chain PEG moieties and facilitated tumor cell internalization of PTX." (PMID 40732329, 2025). "By acting on type IV and V collagens, important components of the extracellular matrix, MMP2 destroys the histological barrier of tumor cell invasion and promotes tumor cell invasion and metastasis." (PMID 39634133, 2025). "Although it usually acts as a tumor suppressor by inhibiting migration and invasion by regulating MMP2 and MMP9, its overexpression in metastatic cases indicates either a compensatory mechanism or context-specific functionality." (PMID 39958058, 2025). "The center of this model is that eHsp90α chaperones and activates MMP2 to promote tumor cell invasion." (PMID 41440009, 2025). "In summary, these findings demonstrate that PreS1‐pHLIP NMs effectively accumulate at tumor sites and respond to the MMP2‐rich TME, releasing PreS1‐pHLIP and mediating its targeted insertion into tumor cell membranes via pHLIP." (PMID 40091501, 2025). "These cells express and activate MMP2, which degrades Collagen IV, thereby further recruiting BMDCs and tumor cells to the lungs." (PMID 41463352, 2025). "This work shows for the first time that MMP-2 not only contributes to tumor progression but also plays a critical role in the immunosuppressive microenvironment of COAD." (PMID 40611940, 2025). "In some contexts, forced overexpression of miR-708 increased MMP2 expression and promoted invasion, highlighting a dual regulatory role in tumor aggressiveness." (PMID 40429954, 2025). "The observed effects of cannabinoids on AGS cells were also studied on gastric xenografts, decreasing the tumor volume by 30% and decreasing invasion (MMP2/MMP9/MMP8)." (PMID 40076652, 2025).
tumor (continued). "To further investigate the role of MMPs in the process of tumor invasion and dissemination, we investigated GA, a naturally occurring plant phenol with known anti-tumor properties, including the inhibition of MMP-2 and MMP-9 activity." (PMID 40869275, 2025). "This role for MMPs in tumor pathophysiology also makes them a potential therapeutic target, and high levels of MMP2, MMP9, MMP15, MMP16 have been shown to be expressed in GBM tumor cells and associated with poor prognoses." (PMID 41400763, 2025). "MMPs are well-known factors associated with the tumour microenvironment (TME); MMP-2 and MMP-10 were identified as diagnostic indicators for PDAC and its progression in several studies." (PMID 37903909, 2024). "Tumor cells have the capacity to generate MMP-2 and MMP-9, which inhibit the expression of tight junction proteins like claudin-5 and ZO-1, consequently causing disruption to the BBB." (PMID 38243240, 2024). "(2003) developed a DNA vaccine targeting MMP-2, which significantly reduced tumor metastases and growth in mouse models." (PMID 39081320, 2024). "The decrease in MMP-9 activity along with MMP-1 or MMP-2 was observed in different tumor cell lines (HCC38, HCC1937, MDA-MB 231, A549) after treatment with blueberry extract or with the flavanone naringenin (100 μM)." (PMID 38540096, 2024). "Several studies have implicated MMP-2 dysregulation in CRC progression, correlating its expression levels with clinicopathological features such as tumor stage, metastasis, and patient survival." (PMID 38978899, 2024). "MMP-2, produced by fibroblasts, is expressed in the initial stages of tumor formation, initiating tumor growth." (PMID 39582871, 2024). "SSX expression affects EMT in tumor cells, and the downregulation of SSX expression can inhibit the promoting effect of vimentin and MMP2 proteins on tumor cell invasion." (PMID 38896069, 2024). "The ENP919@5-FU nanovesicle was easily captured by high expression MMP-2 enzymes in the tumor site, resulting in relative size changes-dependent accumulation and retention in tumor tissue, thereby effectively enhancing tumor cellular uptake." (PMID 38755645, 2024). "Studies have shown that MMP-9 is superior to MMP-2 for tumor recurrence and survival prediction in HCC patients." (PMID 38461536, 2024). "Among these proteases, MMP-2 and MMP-9 are frequently associated with tumor cell migration, invasion, and metastasis." (PMID 39594778, 2024). "It has also been shown that HSP90α and HSP70 secreted by tumor cells promote the activation of matrix metalloproteinase 2 (MMP-2), thereby promoting invasion and migration." (PMID 39027362, 2024). "For instance, the IL-6, platelet-derived growth factor (PDGF), and matrix metalloproteinases (MT-MMPs) such as MMP-2, MMP-9, MMP-14 and alpha-1 type I collagen (encoded by COLA1) secreted by tumour cells are known to influence MSC activity." (PMID 39120301, 2024). "This suggests that high MMP2 expression is correlated with more aggressive and advanced tumor characteristics." (PMID 38978899, 2024). "MMP2 is involved in tumor invasion, angiogenesis, and metastasis, which are key events in cancer progression." (PMID 38560573, 2024). "In the extracellular domain, PEPD and “upstream” metalloproteinases (MMP-2 and -9) have been shown to influence tumor metabolism and to shape microenvironment–tumor interplay." (PMID 38275897, 2024). "The short peptide sequence PLGLAG is an MMP2/MMP9-sensitive linker fragment that breaks in tumor tissue." (PMID 38399294, 2024). "MMP-2 has been found to play a role in tumor invasion and metastasis, particularly in glioma progression, where it interacts directly with the fibronectin receptor α5β1 integrin." (PMID 39769454, 2024). "In hypoxic conditions, type IV collagen is released within the tumor microenvironment and degraded by BMDCs with the involvement of MMP-2, contributing to tumor invasion and the distribution of metastases." (PMID 39769318, 2024).
tumor (continued). "The drug‐loaded peptide DI/Pep1 can actively target tumor tissues and undergo a transformation from a spherical shape to an aggregate shape with a high aspect ratio induced by MMP‐2 in tumor tissues." (PMID 39545088, 2024). "Overall, this study revealed that circ_0051428 executes a tumor-promoting function in CC pathogenesis by modulating the miR-885-3p/MMP2 axis." (PMID 38584845, 2024). "Numerous studies have discovered that the elevated levels of MMP‐2 are the determinants of the aggressive behaviour of tumour cells." (PMID 39121240, 2024). "The MMP family is associated with tumour progression, metastasis and angiogenesis of CRC, and the overexpression of MMP‐2 and MMP‐9 has been known as a sign of poor prognostic factors." (PMID 38506205, 2024). "MMP2 is a metalloproteinase with key functions in the remodeling of the vasculature, angiogenesis, tissue repair, tumor invasion, and inflammation." (PMID 38731868, 2024). "The tumor-bearing animals treated with the polyphenol demonstrated significantly lower MMP-2 and MMP-9 serum concentrations compared to the untreated group." (PMID 39335164, 2024). "In CRC, MMPs, particularly MMP-2 and MMP-9, are implicated in EMT, playing a role in the degradation of type IV collagen in the basement membrane and increasing tumor invasiveness." (PMID 38672844, 2024). "Jiang and co-authors reported that the overexpression of MMP-2 and MMP-9 in cancer cells was linked to poor survival, lymph node metastasis, and larger tumor size." (PMID 39199694, 2024). "Compared with normal cells with inhibited MMPs activity, tumor cells overexpress some MMPs, including MMP2, MMP9, and MMP13." (PMID 39598564, 2024). "To gain a deeper understanding of how MMP2 promotes tumor cell growth and invasion, we inhibited MMP2 expression in the SW480 cell line using an APR100 inhibitor." (PMID 38978899, 2024). "In cancer, MMP-2 facilitates tumor invasion and metastasis by degrading ECM components and promoting angiogenesis." (PMID 39769454, 2024). "Given that mmp2 is necessary for promoting tumor invasion, it potentially accounts for the reduced invasive potential of GBM." (PMID 38520025, 2024). "The peptide is an MMP-2-sensitive linker that can be cleaved in the presence of the MMP-2 enzyme to release DOX in the tumor milieu." (PMID 38398021, 2024). "MMP-2 plays a key role in tumor motility and is overexpressed in oral carcinoma, glioblastoma, bladder cancer, bone metastasis, and sarcoma." (PMID 38816365, 2024). "This platform is enhanced by MMP-2-responsive drug delivery mechanisms and is specifically engineered to increase drug accumulation in tumor regions with dense VM." (PMID 38664830, 2024). "Aqueous extract obtained from Scutellaria baicalensis resulted in a reduction in the expression of MMP-2 by downregulating Cyclin D1, thus hindering the growth and invasion of tumor cells." (PMID 39161904, 2024). "NFATC1 increased BLCA to promote tumor cell growth/colony formation and also promoted tumor migration and invasion by increasing expression of MMP2 and MMP9." (PMID 38910160, 2024). "These nano-PROTACs can sequentially respond to extracellular matrix metalloproteinase-2 (MMP-2), acidic intracellular environments (pH < 6.2), and the reductive tumor microenvironment (GSH) to release the active PROTACs." (PMID 39649701, 2024). "The treatment decreased tumor volume as well as weight by 61% and 43%, respectively, along with downregulating the expression of MMP‐2/9, PCNA, and VEGF." (PMID 39479710, 2024). "Differences were also found in Matrix Metallopeptidase-2, vascular endothelial growth factor, and microvessel density within the enhancing tumor parenchyma of these tumors." (PMID 38952379, 2024). "For example, MMP13 (Matrix Metalloproteinase 13) secreted by fibroblasts promotes tumor angiogenesis, while MMP2 (Matrix Metalloproteinase 2) and MMP9 (Matrix Metalloproteinase 9) degrade ECM (Extracellular Matrix) components to promote metastasis." (PMID 38782818, 2024).
tumor (continued). "It was suggested that these tumor-inhibitory outcomes revealed by RA were achieved via regulation of the miR-506/MMP2/16 signaling pathway." (PMID 39519255, 2024). "The expression of E2F7, MMP2 and Nanog was decreased in tumor tissues with sh-circFKBP8#1 transduction." (PMID 39192374, 2024). "The 4 h LMF exposure caused a significant increase in MMP2 and MMP9, as well as in onco-miRs miR-155, miR-210, miR-21, but a significant reduction in tumour-suppressor miRs (miR-200c and miR-126) in the metastatic PC3 cells, compared with normal PNT2 cells." (PMID 39336161, 2024). "In the literature, MMP-2 and MMP-9 are frequently implicated in the development and expansion of tumor cells in bone metastasis." (PMID 39063556, 2024). "For example, MMP-14 can induce collagen I, II, and III in the tumor extracellular matrix, and MMP-2 and MMP-9 can degrade collagen IV, thus mediating tumor cell invasion into the basement membrane and inducing tumor invasion and metastasis." (PMID 39408814, 2024). "Glabridin downregulates Wnt1, β-catenin, and downstream proteins Cyclin D1, MMP-2, and Survivin, inhibiting the tumor cell cycle." (PMID 39723390, 2024). "The only MMPs with lowered expression in neoplasm tissue were MMP2 and MMP14 independently of the cancer grade." (PMID 38397798, 2024). "This secretion triggers a miR-4488/RTN3/FABP5/MMP2 feedback loop in pNEN cells, highlighting a complex interplay between pNEN cells and the tumor microenvironment that promotes tumor progression and metastasis." (PMID 38904015, 2024). "Previous study has indicated that MMP-2 contributes to the migration and invasion of several tumours via similar mechanisms." (PMID 38594611, 2024). "Immunohistochemical analysis showed that the pJNK, MMP2, and Ki-67 protein levels were significantly increased in tumor tissues of LRP1–SNRNP25-overexpressing cell-injected nude mice." (PMID 38678020, 2024). "MMP2 and MMP9, members of the MMP family, are often involved in poor prognosis and linked to tumor invasion and metastasis in CRC y." (PMID 39520627, 2024). "The same was observed for mmp2 and mmp9, metalloproteases connected to tumor cell invasion, for glucose-phosphate isomerase 1 (gpi1), tnfα, lysyl oxidases (lox, loxl), and the progenitor marker cd44 that is also linked to increased metastasis." (PMID 39095583, 2024). "Following engagement with the extracellular tumor environment, MMP-2/9 cleavage at the intervening PLGC(Me)AG linker within ACPP “activates” the ACPP by removing the spatial inhibition of the polyanionic moiety." (PMID 39683778, 2024). "The activation of the MAPK/ERK pathway is known to contribute to the immune evasion potential of tumor cells, which was further diminished by hesperidin and reduced secretion levels of MMP-9 and MMP-2 in high PD-L1 expressing tumor cells." (PMID 39690423, 2024). "MST1 then recruits macrophages into tumor tissue and macrophage polarization to M2 type, which secrete MMP2 and MMP9 to promote HCC cell dissemination." (PMID 39695147, 2024). "The combination therapy of TACE and RLX can significantly increase the expression of MMP-9 and MMP-2 in tumor tissue (p < 0.001)." (PMID 38955827, 2024). "In concordance, HACE1 suppressed the expression of CCND1, Bcl-2, and MMP2 in tumor tissue, with EHop-016 intensifying the inhibitory effects on these proteins." (PMID 38706891, 2024). "As such, several studies have already found a significant association between MMP-1, MMP-2, MMP-9, and MMP-13 expression and tumor development, as well as aggressiveness and fast metastatic pattern." (PMID 39063046, 2024). "In vitro MMP2 expression is controlled by Tregs, which also prevent the formation of the invasion-promoting factor MMP2 in the tumor microenvironment." (PMID 38602556, 2024). "In this study, immunohistochemical analysis revealed that high expression of MMP2 was significantly correlated with tumor stage, lymph node metastasis, vascular invasion, and perineural invasion." (PMID 38978899, 2024).